SMURF1 (SMAD specific E3 ubiquitin protein ligase 1)
Diseases named in the same sentence as SMURF1 in open-access papers (continued):
Sharing a sentence is not in itself a finding about the gene and the disease.
glioblastoma (7 papers, 2021 to 2024). The most malignant astrocytic tumor (WHO grade IV). "Finally, the mouse xenograft models also confirmed that depletion of SMURF1 markedly suppressed glioblastoma cell growth and proliferation, which was associated with decreased KEAP1-NRF2 pathway." (PMID 37316499, 2023). "Moreover, SMURF1 loss reduces glioblastoma cell proliferation and growth in subcutaneously implanted nude mice xenografts." (PMID 37316499, 2023). "To determine if Smurf1 promotes liquidity of p62, we overexpressed fluorescence-labeled p62 and Smurf1 in glioblastoma cells." (PMID 36810259, 2023). "To further evaluate the role of Smurf1 in the formation of p62 puncta, we knocked down or overexpressed Smurf1 in glioblastoma LN229 cells." (PMID 36810259, 2023). "Here we identify that SMURF1 protects against ER stress and facilitates glioblastoma cell survival by rewiring KEAP1-NRF2 pathway." (PMID 37316499, 2023). "Understanding of molecular mechanism of SMURF1 involved in ER stress response will provide the insight of SMURF1 as a potential target for glioblastoma therapy." (PMID 37316499, 2023). "Our work provides a novel mechanism that SMURF1 defends against ER stress and promotes glioblastoma cell survival through KEAP1-NRF2 pathway." (PMID 37316499, 2023). "Our previous studies have demonstrated that SMURF1 is hyperactivated in glioblastoma and promotes tumor growth by ubiquitination and degradation of tumor suppresser phosphatase and tensin homolog (PTEN)." (PMID 37316499, 2023). "A recent study demonstrates that Smurf1 knockdown reduces glioblastoma (GB) progression through ubiquitination of PTEN." (PMID 34614303, 2022). "In this study, we show that autophagy activators promote Smurf1 degradation in glioblastoma (GB) cells." (PMID 34614303, 2022). "Smad ubiquitination regulatory factor 1 (Smurf1) can mediate PTEN ubiquitylation to promote PTEN wild-type glioblastoma growth." (PMID 34805185, 2021). "Therefore, our findings suggest that SMURF1 is a novel regulator in ER stress and plays a cytoprotective role in glioblastoma." (PMID 37316499, 2023). "Taken together, our study highlights a crucial role of SMURF1 in maintaining ER homeostasis, and SMURF1 may be a potential target for glioblastoma therapy." (PMID 37316499, 2023). "Further studies are needed to explore the molecular mechanisms of glioblastoma through which ER stress induces the degradation of SMURF1, and how to mediate its pro-survival effects and whether there is a feedback regulation mechanism affecting SMURF1." (PMID 37316499, 2023). "Furthermore, SMURF1 depleted tumor showed downregulation of NRF2 expression, and upregulation of KEAP1 expression compared to the control tumor xenografts, suggesting that SMURF1-induced KEAP1-NRF2 pathway plays a vital role in glioblastoma growth." (PMID 37316499, 2023). "The highly expressed SMURF1 in glioblastoma cells is required for ER homeostasis maintenance." (PMID 37316499, 2023). "ER stress and SMURF1 modulation may provide promising therapeutic targets for the treatment of glioblastoma." (PMID 37316499, 2023). "Taken together, SMURF1 rewires KEAP1-NRF2 pathway to confer resistance to ER stress inducers and protect glioblastoma cell survival." (PMID 37316499, 2023). "Therefore, targeting SMURF1 and KEAP1-NRF2 signaling pathway may be potential cancer therapy for glioblastoma or ER stress-related disease." (PMID 37316499, 2023).
osteoporosis (7 papers, 2007 to 2024). A condition of reduced bone mass, with decreased cortical thickness and a decrease in the number and size of the trabeculae of cancellous bone (but normal chemical composition), resulting in increased fracture incidence. "Consistent with these molecular mechanisms, clinical features in the reported child with osteoporosis and bone fractures showed phenotypic similarity to those observed in mice with Smurf1 mutations." (PMID 36911671, 2023). "Furthermore, a clinical case recently linked osteoporosis with a Smurf1 gene mutation, in which a 10-year-old girl was diagnosed with fractures and low bone mineral density, and a pathogenic microduplication involving the Smurf1 gene was detected by array comparative genomic hybridization." (PMID 36077334, 2022). "Belonging to the C2-WW-HECT region Ub ligases, Smurf1 downregulates the level of alkaline phosphatase and osteocalcin and suppresses the osteogenic activity of osteoblasts, resulting in osteoporosis and fragility fractures." (PMID 38940355, 2024). "As the major E3 ligase in the differentiation processes of osteogenic lineage, treatment of osteoporosis by targeting SMURF1 has been proposed." (PMID 37799379, 2023). "Behaviors of OBs and OCs during osteoporosis are also controlled by the alteration of Smurf1 mRNA level." (PMID 37799379, 2023). "In addition to SMURF1, WWPs regulation is also depicted to resist osteoporosis." (PMID 37799379, 2023). "Being manifested as low SMURF1 activity, mice treated with 2-(4-cinnamoylphenoxy) acetic acid, the chalcone derivative, are free from OVX-induced osteoporosis." (PMID 37799379, 2023). "The study also found that miR-195-5p achieved BMP-2/Smad/Akt/RUNX2 axis activation by targeting and suppressing Smurf1 to accelerate osteogenic differentiation of MC3T3-E1 in vitro and relieve osteoporosis progression in an ovariectomized (OVX) mouse model." (PMID 36077334, 2022).
viral infection (7 papers, 2018 to 2025). "Upon a comparison of LDH release in both phenotypes following infection, we observed lower levels of LDH release in cultures of Smurf1−/− BMDMs infected with MHV-A59, indicating that Smurf1−/− BMDMs demonstrated increased cell viability compared to wild-type macrophages upon viral infection." (PMID 39452742, 2024). "The role of Smurf1 in regulating TRAF3/TRAF6 protein levels during viral infection remains unknown so far, although Smurf1 was reported to be able to bind to and ubiquitinate exogenous Myc-TRAFs family members in HEK293T cells." (PMID 29734366, 2018). "Therefore, we further observed the role of Smurf1 in OTUD1-mediated inhibitory effect on IFNs production during viral infection." (PMID 29734366, 2018). "Finally, the deubiquitinase OTUD1 potently inhibits RLR pathway by utilizing Smurf1-MAVS/TRAF3/TRAF6 signaling at the early stage of viral infection." (PMID 29734366, 2018). "Given that MAVS is a mitochondrial protein and Smurf1 can regulate MAVS/TRAF3/TRAF6 proteins during RNA virus infection, we speculate that upregulated Smurf1 proteins by viral infection could be able to localize to the mitochondria to interact with the MAVS/TRAF3/TRAF6 signalosome." (PMID 29734366, 2018). "This indicated that the function of some E3 ligases (e.g., Smurf1) to interact and degrade MAVS is enhanced in the early and middle stages of viral infection." (PMID 39665545, 2025). "For instance, OTUD1 increases Smurf1 expression levels to promote degradation of the MAVS/TRAF3/TRAF6 signalosome and inhibit the innate immune response to viral infection." (PMID 35280681, 2022). "We next sought to determine how viral infection affects the levels of OTUD1, Smurf1 and MAVS/TRAF3/TRAF6, and whether the regulation signaling of OTUD1-Smurf1-MAVS/TRAF3/TRAF6 occurs during viral infection." (PMID 29734366, 2018). "Here, our results indicate that OTUD1 could utilize Smurf1 to downregulate MAVS/TRAF3/TRAF6 proteins and restrict IFNs production during viral infection." (PMID 29734366, 2018).
pulmonary arterial hypertension (6 papers, 2019 to 2025). Pulmonary arterial hypertension (PAH) is a group of diseases characterized by mean pulmonary artery pressure >20 mmHg and elevated pulmonary arterial resistance leading to right heart failure. "SMURF1 levels are increased in pulmonary arterial hypertension (PAH), a disease caused by mutation of bone morphogenetic protein receptor-2 (BMPR2)." (PMID 40179885, 2025). "SMAD-specific E3 ubiquitin protein ligase 1 (SMURF1) is associated with pulmonary arterial hypertension (PAH)." (PMID 36552825, 2022). "A large, unbiased biochemical screen discovers inhibitors of SMURF1 that reverse established pulmonary arterial hypertension by extending an α helix over a conserved glycine hinge to restrict the essential catalytic motion." (PMID 40179885, 2025). "WWP2 is involved in vascular endothelial injury 123-124, SMURF1 in atherosclerosis 135-137 and pulmonary hypertension 127-132, and SMURF2 in myxomatous mitral disease 158-160 and vascular endothelial injury 168-170." (PMID 33110392, 2020). "Moreover, the idea of SMURF1 inhibition in patients has gained interest as a potential therapeutic strategy in other clinical contexts including pulmonary hypertension and macular degeneration." (PMID 40076507, 2025). "There is a compelling rationale for targeting SMURF1 in the treatment of pulmonary arterial hypertension (PAH)." (PMID 40179885, 2025). "SMURF1 functions as an E3 ubiquitin ligase protein and has been shown previously to regulate endocytosis of other membrane proteins such as the bone morphogenetic protein type II receptor (BMPR), related to pulmonary arterial hypertension." (PMID 31231217, 2019).
liver cancer (5 papers, 2018 to 2024). An epithelial or non-epithelial malignant neoplasm that arises from the liver. "Xu and coworkers reported that TRIB2 suppressed the Wnt/TCF4 pathway through several E3 ligases, including β-TrCP, COP1, and Smurf1, in liver cancer cells." (PMID 39199296, 2024). "TRIB2 is also specifically regulated by Wnt signaling in liver cancer cells, which is associated-Ub E3 ligase-TrCP, RFWD2, and Smurf1 reducing TCF4/β-catenin expression." (PMID 34646775, 2021). "In addition, SMURF1 increases the protein stability of β-TrCP by reducing the autoubiquitination of β-TrCP in liver cancer cells." (PMID 37686524, 2023). "Future studies are necessary to ascertain the tissue origin of the steatogenic effect of Smurf1 ablation using conditional knockout approaches and to determine if and how BL-Smurf1 mice could be enticed to progress through NASH or even liver cancer to model the entire NAFLD disease spectrum." (PMID 30566427, 2018). "Another study reported that the dysregulation of phosphorylation and ubiquitination by p70S6K and Smurf1 led to the stability of TRIB2 and an oncogenic phenotype in liver cancer." (PMID 39199296, 2024). "In addition, TRIB2 contributes to the negative regulation of WNT/β-catenin/TCF4 signaling specifically in liver cancer cells by physically binding to β-TrCP, COP1, and SMAD ubiquitination regulatory factor 1 (SMURF1)." (PMID 37686524, 2023). "Furthermore, TRIB2 has been revealed to interact with E3s including Smurf1, COP1, and βTrCP in liver cancer cells." (PMID 34315867, 2021).
renal fibrosis (5 papers, 2015 to 2025). A final common manifestation of a wide variety of chronic kidney diseases characterized by glomerulosclerosis and tubulointerstitial fibrosis. "A previous study illustrated that SMURF1 upregulation caused an increase of high glucose (HG)-induced renal fibrosis in glomerular mesangial cells and diabetic mice kidneys." (PMID 35194023, 2022). "It is interesting to note that in mice Smurf1/2 have been implicated in the regulation of planar cell polarity and renal fibrosis." (PMID 26147758, 2015). "In conclusion, miR-154-5p can affect proliferation in glomerular mesangial cells via E3 ubiquitin ligase, Smurf1, regulating TGFβ1/Smads pathway, thus affecting renal fibrosis of DKD." (PMID 35126820, 2022). "The expression of genes that promote renal fibrosis (Smad2, Smad3, Smad4, Shh, Dll1) was downregulated, while the expression of genes that inhibit renal damage (Smurf1, Smurf2, Smad1, Smad5, Smad6, Smad7) was increased in the WT+miPEP31 group (PEP1/2) compared with the WT+ cPEP (SCR1/2) group." (PMID 38992718, 2024). "For example, Smurf1 plays a role in various diseases such as DKD and renal fibrosis and can interact with deubiquitinating enzymes to influence disease progression." (PMID 40225869, 2025).
hepatocellular carcinoma (4 papers, 2018 to 2022). A malignant tumor that arises from hepatocytes. "Notably, a prior work indicated that SMURF1 ubiquitinated UV radiation resistance-associated gene (UVRAG) to induce autophagosome maturation in hepatocellular carcinoma." (PMID 35194023, 2022). "A recent study reported that the Smurf1-induced UVRAG ubiquitination promotes not only autophagosome maturation but hepatocellular carcinoma (HCC) growth." (PMID 31630678, 2019). "We also show that overexpression of SMAD6 and SMURF1 in hepatoma cells inhibited HAMP-Luc activity, while endogenous MyD88 protein expression diminished." (PMID 30234111, 2018).
lung carcinoma (4 papers, 2018 to 2023). "In order to confirm the results of enrichment analysis of NEDD4 family members-interacted proteins, we transfected plasmids of Smurf1, Smurf2 in A549 and H1299 lung cancer cells." (PMID 37291499, 2023). "After transfection of NEDD4 family members Smurf1 and Smurf2, the lung cancer cells H1299 were subjected to cisplatin (a commonly used chemotherapy drug) treatment to detect the difference of apoptosis in relation to Smurf1 and Smurf2." (PMID 37291499, 2023). "On contrast, transient silence of Smurf1 and Smurf2 by si-RNAs promoted apoptosis in H1299 lung cancer cells." (PMID 37291499, 2023). "At times, phosphorylation can completely reverse the original effect of Smurfs on tumors, such as PKA inhibiting lung cancer cell growth by decreasing Smurf1 activity." (PMID 33718111, 2020). "The staining of total SRSF5 and acetylated SRSF5 increased, while the Smurf1 expression level decreased moderately, in lung cancer samples compared with their adjacent tissues and accumulation of positive signals in nucleus were observed." (PMID 29942010, 2018). "Furthermore, our results of flow cytometric analysis suggested that both Smurf1 and Smurf2 suppressed apoptosis in H1299 lung cancer cells, which were in consistence with previous reports of the involvement of Smurf1 and Smurf2 in apoptosis." (PMID 37291499, 2023). "Finally, we found that both Smurf1 and Smurf2 suppressed apoptosis in H1299 lung cancer cells." (PMID 37291499, 2023). "Among them, SMURF1, MDM2, SMURF2, TRIM27, and NEDD4L are involved in lung cancer progression." (PMID 33264103, 2020).
osteonecrosis (4 papers, 2020 to 2025). A none disease characterized by death of bone tissue due to a lack of blood supply. "The miR-148a-3p in MSC exosomes can prevent the osteonecrosis of the femoral head by inhibiting the expression of Smad ubiquitination regulatory factor 1 (SMURF1)." (PMID 34899907, 2021). "Indeed, identification of microRNA-148a-3p as the mediator of the beneficial effect of BMSC EVs on osteonecrosis confirmed the role of SMURF1 in the pathogenesis." (PMID 34571848, 2021). "Collectively, the miR-148a-3p/SMURF1/SMAD7/BCL2 axis contributes to maintaining osteoblast viability and bone integrity, thereby alleviating osteonecrosis of the femoral head." (PMID 41511311, 2025).
thyroid cancer (4 papers, 2019 to 2022). "When cultured thyroid cancer cells were transfected with Smurf1, Kisspetin-1 protein levels declined in a dose-dependent fashion." (PMID 35406382, 2022). "Recently more studies indicated the potential role of miR-4319 in inhibiting thyroid cancer by controlling FUS‐stabilized SMURF1." (PMID 34391433, 2021). "In additional experiments, the overexpression of Smurf1 in cultured thyrocytes stimulated migration, invasion, and proliferation of the cells, suggesting that Smurf1 may be involved in thyroid cancer aggressiveness." (PMID 35406382, 2022).
clear cell renal cell carcinoma (3 papers, 2017 to 2025). "For instance, FBXW10 gene is found to be hypermethylated in clear cell renal cell carcinoma, while FBXO3 influences TGF‐β signaling by targeting SMURF1 for proteasomal degradation." (PMID 28397399, 2017).
glioma (3 papers, 2020 to 2022). A benign or malignant brain and spinal cord tumor that arises from glial cells (astrocytes, oligodendrocytes, ependymal cells). "proved that SMURF1 was associated with glioma cell migration." (PMID 35280808, 2022). "SMURF1 expression is upregulated in GB and mediates metastasis in gliomas by promoting epithelial to mesenchymal translation (EMT), whereas SMURF1 suppression reverses these oncogenic effects." (PMID 32984016, 2020). "Meanwhile SMURF1 knockdown dramatically inhibits glioma cell proliferation and growth." (PMID 32984016, 2020).
head and neck squamous cell carcinoma (3 papers, 2014 to 2025). A squamous cell carcinoma that arises from any of the following anatomic sites: lip and oral cavity, nasal cavity, paranasal sinuses, pharynx, larynx, and salivary glands. "In addition, SMURF1 is required for the maintenance of stemness of tumor stem cells in head and neck squamous cell carcinoma (HNSCC)." (PMID 40342823, 2025).
heart failure (3 papers, 2020 to 2023). Inability of the heart to pump blood at an adequate rate to meet tissue metabolic requirements. "This miRNA, partially transported in exosomes, acts as the link between the lung and the heart modulating the expression of smad ubiquitination regulatory factor 1 (SMURF1) and contributing to right ventricle hypertrophy and heart failure." (PMID 37626985, 2023). "Raised Activin type II receptor signaling links aging and the pathobiology of heart failure through the regulation of follistatin-like 3 and Smurf1." (PMID 35034538, 2022). "Previous research has identified the involvement of Smurf1 in heart failure." (PMID 35034538, 2022).
Myocardial fibrosis (3 papers, 2020 to 2024). "The Smurf1/Smad6 complex antagonizes the myocardial fibrosis signal enhanced by TGF-β1/rock." (PMID 35034538, 2022). "Therefore, Smurf1 downregulation by mir-10b-5p could blunt the anti-fibrotic effect of hypoxia, and SMURF1 has a potential function in alleviating myocardial fibrosis." (PMID 33110392, 2020). "Several E3 ubiquitin ligases, such as WWP2, SMURF1, and SMURF2, have been identified as key regulators in myocardial fibrosis." (PMID 39055656, 2024).
chronic heart failure (2 papers, 2022 to 2024). "In a study involving rats with chronic heart failure, miR-129-5p was found to inhibit PTEN ubiquitination and enhance PTEN expression by targeting Smurf1." (PMID 38203803, 2024).